PVT1 (Pvt1 oncogene)
Diseases named in the same sentence as PVT1 in open-access papers (continued):
Sharing a sentence is not in itself a finding about the gene and the disease.
colorectal cancer (86 papers, 2010 to 2026). A primary or metastatic malignant neoplasm that affects the colon or rectum. "Colorectal cancer cell lines resistant to 5-FU demonstrated overexpression of non-coding RNA plasmacytoma variant translocation 1 (PVT1), which suppressed apoptosis." (PMID 40777019, 2025). "In colorectal cancer samples, PVT1 gene expression increased 10-fold, associated with an enrichment of CD8+ T cell subsets in colorectal cancer lesions." (PMID 36831498, 2023). "fabricated complex liposome systems consisting of colorectal cancer cell membranes, short hair‐pinned RNA (shRNA) against plasmacytoma variant translocation 1 (Pvt1), 1,2‐Dioleoyl‐3‐trimethylammonium propane (DOTAP), and oxaliplatin." (PMID 36479842, 2023). "LncRNA plasmacytoma variant translocation 1(PVT1) is located on chromosome 8 of the c-Myc gene and is abnormally expressed in multiple malignancies, including nasopharyngeal carcinoma, colorectal cancer, ovarian cancer, and so on." (PMID 37263709, 2023). "In colorectal cancer, the expression of PVT1 isoform Sv-214 was found to be positively associated with tumor size, advanced stage (III-IV), distant metastasis, and reduced overall and disease-free survival." (PMID 32083000, 2020). "Specifically, we evaluate the potential role of lncRNA plasmacytoma variant translocation 1 (PVT1), an oncogene, as a diagnostic, prognostic, and therapeutic biomarker in colorectal cancer." (PMID 32726923, 2020). "They found PVT1 Sv-214, Sv-205, Sv-209, Sv-208, Sv-206, Sv-207, Sv-213, Sv-219, Sv-201, and Sv-215 upregulated in colorectal cancer vs. normal samples (variants ranked by decreasing overexpression fold)." (PMID 32083000, 2020). "In colorectal cancer, the elevated level of PVT-1 causes inhibition of colorectal cancer cells sensitivity to 5-FU." (PMID 35582574, 2019). "Amplification of PVT-1 is associated with poor prognosis via inhibition of apoptosis in colorectal cancer." (PMID 29340250, 2018). "lncRNA PVT1 has been implicated in the progression of colorectal cancer via the VEGFA-AKT axis." (PMID 40225268, 2025). "Notably, PVT1 knockdown led to a remarkable loss of lung and colorectal cancer cell proliferation and invasion in vitro." (PMID 36624401, 2023). "Association between PVT1 rs2278176 and colorectal cancer patient’s clinical outcome." (PMID 35433465, 2022). "Moreover, genome-wide association studies (GWAS) identified single nucleotide polymorphisms (SNPs) in the PVT1 locus (8q24) that are associated with increased colorectal cancer risk." (PMID 32083000, 2020). "Moreover, PVT1 accelerates cell proliferation, migration and invasion of colorectal cancer cells in vitro, and tumorigenesis in vivo, with the underlying mechanism of simulating RUNX2 expression by inhibiting miR-455 activity." (PMID 31497532, 2019). "Moreover, depletion of PVT1 by small interference RNAs (siRNAs) caused the reduction of MYC protein levels in a human colorectal cancer cell line and nuclear colocalization of PVT1 and MYC was also shown." (PMID 25883951, 2015). "In addition, The upregulation of PVT1 resulted in elevated mRNA and protein expression levels of multidrug resistance-associated protein 1,and apoptosis regulator Bcl2, which enhanced drug resistance in colorectal cancer cells." (PMID 39830506, 2024). "Our results showed that PVT1 overexpression is specific for STAT3-mutated T-LGLL, also providing evidence of a STAT3-dependency, similarly to what observed in colorectal cancer, where a STAT3-PVT1 feed-forward regulatory loop was described." (PMID 40721648, 2025). "PVT1 is known to be abnormally expressed in several malignant tumors, including nasopharyngeal carcinoma, esophageal cancer, and colorectal cancer." (PMID 40078998, 2025). "In the study on colorectal cancer, Hsa-circ-PVT1 was discovered to bind miR-145 as a “molecular sponge,” thereby upregulating the expression of the MAPK1 gene and promoting the proliferation, invasion, and angiogenesis of endometrial stromal cells." (PMID 41584514, 2025).
colorectal cancer (continued). "In colorectal cancer tissues and extracellular vesicles, PVT1 and c-Myc are co-amplified, which in turn promotes the proliferation and metastasis of colorectal cancer cells." (PMID 39830506, 2024). "For instance, PVT1 has been shown to promote cervical cancer progression by silencing miR-200b and support colorectal cancer cells by inhibiting apoptosis." (PMID 36624401, 2023). "PVT1 is also highly expressed in colorectal cancer tissue, and downregulating PVT1 reduces malignant behaviors, including cell proliferation, migration, and invasion." (PMID 37573419, 2023). "Accumulating evidence suggests that the PVT1 locus as an epigenetic enhancer in colorectal cancer (CRC) and it has a regulatory effect on regulating the expression of MYC." (PMID 35392800, 2022). "In colorectal cancer patients, upregulated PVT1 was positively correlated with cell proliferation, invasion, tumour stages, and lymph node metastasis." (PMID 35501730, 2022). "Patients with colorectal cancer with high PVT1-214 expression have a shorter survival duration and poor prognosis." (PMID 34336125, 2021). "A recent study indicated that lncRNA PVT1 promotes the tumorigenesis of colorectal cancer by stabilizing miR-16-5p and interacting with the VEGFA/VEGFR1/AKT axis." (PMID 34336125, 2021). "Because advanced colorectal cancer can be defined as colorectal cancer that metastasizes when it appears or recurs, we analyzed the difference in PVT1 expression between primary and metastatic tumors from the GSE49355 dataset." (PMID 34336125, 2021). "Further analysis indicated that the expression of PVT1 in advanced colorectal cancer was more significant." (PMID 34336125, 2021). "Previous studies have demonstrated that lncRNA PCGM1, GHET1, CCAT1-L, and PVT1 regulate Myc transcription or RNA and protein stability in the prostate, gastric, and colorectal cancers." (PMID 34696771, 2021). "Recent studies have demonstrated that PVT1 regulates the VEGFA/VEGF receptor 1 (VEGFR1)/AKT axis and promotes the tumorigenesis of colorectal cancer; the deletion of PVT1 can reduce tumor volume." (PMID 34336125, 2021). "Our analysis of a pan-cancer cohort from the Cancer Genome Atlas (TCGA) public cancer database showed that patients with colorectal cancer exhibited a higher PVT1 expression level." (PMID 34336125, 2021). "Some studies have reported that the expression of lncRNA PVT1 is aberrant in different malignant tumors, including breast, gastric, and colorectal cancers." (PMID 32960485, 2021). "By regulating the miR-106b-5p/FJX1 axis, knockdown of PVT1 can impair cell proliferation, migration, and invasion in colorectal cancer." (PMID 34336125, 2021). "Plasmacytoma variant translocation 1 (PVT1) has been extensively investigated in cancers, including lung cancer, colorectal cancer, and ovarian cancer where PVT1 was promoted and facilitated cell proliferation and invasion." (PMID 32293498, 2020). "Of note, all the cell lines used in these studies were all MYC amplified, and in the case of the colorectal cancer cell lines, also PVT1 amplified." (PMID 32083000, 2020). "PVT1 knockdown hinders cell proliferation and invasion in colorectal cancer due to up-regulated miR-214-3p." (PMID 32808668, 2020). "PVT1 is clearly dysregulated in gastric and colorectal cancer, and experimental mechanistic studies convincingly demonstrate that elevated levels of this lncRNA promote proliferation, angiogenesis and metastasis in human malignancies." (PMID 32083000, 2020). "PVT1 promotes the development of cisplatin resistance in colorectal cancer; thus, silencing PVT1 inhibits tumorigenesis and cisplatin resistance in colorectal cancer." (PMID 31309249, 2019).
colorectal cancer (continued). "LncRNA plasmacytoma variant translocation 1 (PVT1) is suggested to promote tumorigenesis in several cancers including ovarian cancer, colorectal cancer, and lung cancer, among which PVT1 is upregulated and induced cell proliferation and invasion." (PMID 31303891, 2019). "Abnormal PVT1 expression has been shown to be a powerful predictor of cancer progression and patient survival in colorectal cancer, hepatocellular carcinoma and lung cancer." (PMID 30679629, 2019). "The lncRNA Pvt1 oncogene (PVT1) is related to poor prognosis by inhibiting apoptosis in colorectal cancers." (PMID 29618386, 2018). "Knockdown of PVT1 inhibited cell proliferation, invasion, and activated apoptotic signaling pathway in colorectal cancer cells." (PMID 29108264, 2017). "Many previous references have reported the physiological and pathological roles of PVT1, such as in the diabetic nephropathy and colorectal cancer." (PMID 29046366, 2017). "Promote proliferation and invasion; Knockdown of PVT-1 promotes apoptosis in colorectal cancer cell lines by activating the TGF-β signalling pathway." (PMID 27888635, 2017). "Amongst these was Pvt1, a lncRNA previously reported to be a marker of poor prognosis in colorectal cancer and shown to be required in MYC-driven cancers." (PMID 28875933, 2017). "PVT1 was a reliable diagnosis biomarkers for lung cancer, hepatobiliary cancer, renal tumor, colorectal carcinoma with the AUCs being 0.946 (0.924–0.969), 0.881 (0.849–0.913), 0.952 (0.938–0.967), 0.968 (0.934–0.999), respectively." (PMID 29088881, 2017). "The authors found that colorectal cancer patients with high PVT1 expression had a significantly poorer prognosis than those with low PVT1 expression (P = 0.0101)." (PMID 27148353, 2016). "Knockdown of PVT1 significantly inhibited colorectal cancer cells proliferation and reduced invasive abilities compared with negative control cells." (PMID 27148353, 2016). "Other studies have verified the role of PVT1/miR-486-5p in colorectal cancer." (PMID 39317938, 2024). "Studies have shown that the expression of PVT1 is up-regulated in colorectal cancer." (PMID 39830506, 2024). "Targeting PVT1 could be a potential therapeutic approach for colorectal cancer patients, potentially leading to the inhibition of oncogenic MYC at both RNA and protein levels." (PMID 39830506, 2024). "In colorectal cancer, lncRNA PVT1 has been reported to stabilize MYC protein." (PMID 39830506, 2024). "Chai et al19 demonstrated that the overexpression of lncRNA PVT1 promotes the invasion, migration, and proliferation of colorectal cancer cells in vitro and that lncRNA PVT1, which functions as a competitive endogenous RNA, regulates tumor growth by sponging miR‐455." (PMID 32960485, 2021). "The influence of PVT1 and MALAT1 variants on colorectal cancer (CRC) susceptibility and their impact on PVT1/miRNA-186/epithelial-mesenchymal transition (EMT) and MALAT1/miRNA-101/EMT axes in CRC are unknown." (PMID 34200314, 2021). "Upregulating PVT1 significantly decreased cisplatin resistance in colorectal cancer." (PMID 31249809, 2019). "A recent study demonstrated that PVT1 can generate antiapoptotic activity in colorectal cancer cells and abnormal expression of this gene could be a prognostic factor in colorectal cancer patients." (PMID 31612869, 2019). "Mice injected with clear cell renal cell carcinoma, colorectal cancer, or glioma cells overexpressing PVT1 displayed significantly larger tumor volume than control cells, while those injected with cells with knockdown of PVT1 displayed significantly smaller tumor volume." (PMID 31249809, 2019). "In colorectal cancer, patients with elevated expression of PVT1 also show poorer prognosis." (PMID 31497532, 2019).
colorectal cancer (continued). "lncRNA PVT1-214 enhances cell invasion and proliferation by sponging miR-128 in colorectal cancer." (PMID 31631065, 2019). "PVT1 was a novel lncRNA which was first discovered in 2013 in human colorectal cancer." (PMID 30083911, 2019). "Moreover, PVT1 expression was up-regulated in colorectal cancer tissues, which correlated with the expression of MYC and many MYC regulating genes FUBP1, EZH2, and NPM1." (PMID 29108264, 2017). "Especially, lncRNA PVT1 was detected in extracellular vesicles of colorectal cancer cells." (PMID 29108264, 2017). "Highly expressed PVT1 was a prognostic factor for overall survival of colorectal cancer patients." (PMID 29108264, 2017). "PVT1 has been reported to be an oncogene in colorectal cancer (CRC), the knockdown of which could inhibit cell proliferation and the invasion capabilities of CRC cells via TGF-beta signaling and apoptotic pathways." (PMID 27147563, 2016). "Plasmacytoma variant translocation 1 (PVT1) expression was reported to be upregulated in various tumors, including lung carcinomas, osteosarcomas, squamous cell carcinomas, stomach carcinomas, liver carcinomas, colorectal carcinomas, and nasopharyngeal carcinomas." (PMID 36605618, 2023). "Moreover, down-regulated PVT1 promotes colorectal cancer cells apoptosis." (PMID 27148353, 2016). "Furthermore, real time PCR demonstrated PVT1 may be a new oncogene and has the functional correlation with the proliferation and apoptosis of colorectal cancer cells." (PMID 26061969, 2015). "In colorectal cancer, lncRNA PVT1 has a correlated expression with c-Myc and its regulating genes (NPM1, FUBP1, and EZH2); PVT1 targeted siRNA that transfected SW480 and SW620 cell lines." (PMID 35159299, 2022). "In this study, gene expression analyses indicated that the expression of some PVT1 spliced linear transcripts, CircPVT1, CASC11, and MYC is increased in colorectal cancer (CRC)." (PMID 36052265, 2022). "For example, circ3823 was more stable than PVT1, promoting colorectal cancer growth, metastasis, and angiogenesis through the circ3823/miR-30c-5p/TCF7 axis, and it may serve as a new diagnostic marker or therapeutic target for the treatment of colorectal cancer patients." (PMID 35302432, 2022). "In the current study, we aimed to evaluate the expression as well as the possible relationship among MYC, PVT1, and CASC11 in colorectal cancer." (PMID 36052265, 2022). "To elucidate the role of PVT1, CASC11, and MYC in CRC, we assessed the expression levels of these genes using qRT-PCR for cancerous and adjacent normal tissues from colorectal cancer patients." (PMID 36052265, 2022). "The first evidence of PVT1 in human solid malignancies, and also its relationship with MYC, came from the study of COLO320, a colorectal cancer cell line that was known to be MYC amplified." (PMID 32083000, 2020). "MALAT-1, HOTAIR, PVT-1 and CCAT1-L are up-regulated in colorectal cancer tissue while ncRAN is down-regulated." (PMID 25119862, 2014). "To further investigate this phenomenon, we examined three diverse cancer cell lines that harbored MYC/PVT1 amplification and PVT1 translocations: COLO-320DM (colorectal cancer), SK-PN-DW (primitive neuroectodermal tumor (PNET)), and D458 (medulloblastoma (MB))." (PMID 40027648, 2025). "The PVT1 gene functions as a newly discovered oncogenic enhancer of MYC, and its activity is regulated by epigenetic mechanisms involving abnormal methylation in colorectal cancer." (PMID 39830506, 2024). "In studies on other types of cancer, such as in colorectal cancer and bladder cancer cell lines, BRD4-bound circRNA regulates MYC expression, and BRD4 bound the super-enhancer regulates expression levels of lncRNA PVT1 and MYC." (PMID 36895010, 2023). "However, not all colorectal cancer cell lines exhibit aggressive behavior which is attributable to the expression of PVT1." (PMID 37519802, 2023).
colorectal cancer (continued). "Additionally, PVT1 was found to upregulate the expression of numerous drug resistance-related molecules (e.g., MDR1 and MRP1) and inhibit apoptosis signaling, promoting cisplatin resistance in colorectal cancer." (PMID 34564701, 2021). "These include but are not restricted to lncRNAs like HOTAIR, Pvt1, RoR, prostate cancer–associated transcript 1 (PCAT1), ANRIL, H19, nuclear enriched abundant transcript 1 (NEAT1), UCA1, lung adenocarcinoma transcript 1 (LUADT1), colorectal cancer–associated lncRNA (CCAL), and many more." (PMID 30296263, 2018).